CXCR1 (C-X-C motif chemokine receptor 1)
Diseases named in the same sentence as CXCR1 in open-access papers (continued):
Sharing a sentence is not in itself a finding about the gene and the disease.
infection (continued). "Recently we examined the role of polymorphisms at CXCR1 and CXCR2, which act as receptors for CXC chemokines that attract PMN to inflammatory sites, in determining susceptibility to cutaneous forms of leishmaniasis caused by infection with L. braziliensis." (PMID 22171941, 2011). "Therefore, although neutrophils are crucial for the ability of the murine host to cope with IAV infection, the partial blockade attained with CXCR1/2 antagonists preserves the host immune response to infection but decreases the exacerbated pulmonary inflammation that causes morbidity." (PMID 29326698, 2017). "At times early following infection, multiple transcripts encoding proinflammatory molecules were increased, including IL8 (8196-fold), IL1B (1559-fold), oncostatin M (OSM, 799-fold), CCR1 (588-fold), CXCR1 (625-fold), CXCR2 (596-fold), CCL4 (514-fold), and CCL3 (658-fold)." (PMID 25719526, 2015). "However, since depletion of neutrophils prior to infection promotes survival, individuals chronically administered CXCR1/2 antagonists may experience some level of protection during WNV infection." (PMID 25324719, 2014). "Here the authors show in vitro that infection by the enterovirus, EV-D68, induces CXCL8/CXCR1/2 signaling and translocation of host factor, hnRNP-K, to the cytoplasm as a means to facilitate viral replication." (PMID 39962077, 2025). "CXCR1 and CXCR2, both present on neutrophils, play an important role in granulocyte recruitment to the site of infection." (PMID 35163035, 2022). "Lower magnitudes of gene regulation was noted in this study after infection compared to ferrets infected with the H1N1 virus A/California/07/2009 although immune response genes such as CCL2, CCL8, CXCL9, and CXCR1 increased over the time course." (PMID 34267262, 2021). "CXCR1/2 Inhibitors: CXCR1 and CXCR2 are chemokine receptors that mediate neutrophil recruitment to the site of infection and activation of their antimicrobial activities." (PMID 30987351, 2019). "Studies to investigate the role of specific cytokines and chemokines in the response to infection have shown that these mediators can be beneficial (e.g., IL-6, TNF-α, IL-1, and CXCR1) (62, –, 65), or they can be detrimental (CCR1)." (PMID 29666281, 2018). "Our results show that CXCL8 mediates productive infection of HIV-1 in MDM and microglia via receptors CXCR1 and CXCR2." (PMID 24662979, 2014). "Our study was not sufficiently powered to look for interaction between the CXCR1 and SLC11A1 in this study, and further work will be needed to determine whether the association at SLC11A1 relates to its role in PMN, macrophages or dendritic cells at the site of infection." (PMID 20089160, 2010). "In this online database, the CXCR1 expression was also scarce and did not change during the time course of the infection, while the CXCR2 expression was expressed basally and further induced by the EBV infection." (PMID 36992360, 2023). "Based on these findings, the authors investigated neutrophil CXCR1 expression in 12 children with rUTI but without an active infection (7 of whom had VUR) and in 12 age-matched controls." (PMID 35860746, 2022). "CXCR1 and its ligand C-X-C motif chemokine ligand 8 (CXCL8)/interleukin 8 (IL-8) have been reported in multiple fish species and fish CXCL8/IL-8 is also induced in spleen upon infection with VHSV and IHNV." (PMID 32986779, 2020). "CXCR1, and mainly CXCR2 expression, on neutrophils grants an additional form of chemotaxis away from the bone marrow via their respective ligands, CXCL1 and CXCL2, which are produced by macrophages and mast cells at the site of infection." (PMID 30791481, 2019). "Teleost CXCR1 and CXCR2 are conserved receptors for interleukin-8 (IL-8, also termed CXCL8) and are important for the regulation of neutrophil recruitment and migration to sites of infection and injury." (PMID 30837998, 2019).
infection (continued). "We have also previously shown that zebrafish Cxcr1 is required for neutrophil recruitment to sterile wounds but not to infection and is dispensable for normal neutrophil development and random motility." (PMID 30185911, 2018). "In this study, the expression of trout CXCR1–3 in response to an acute Gram-negative bacterial (Y. ruckeri) infection and a chronic parasitic (T. bryosalmonae) infection was investigated." (PMID 24613851, 2014). "Following infection of trout with a common Gram-negative bacterial pathogen, Y. ruckeri, the expression level of CXCR1 in HK was significantly up-regulated (up to 18.4-fold) from 24 to 72 h relative to time matched control fish." (PMID 24613851, 2014). "Based on the expression pattern of these molecules, we analyzed the frequency of human CD8+ T cells expressing CX3CR1 and/or CXCR1 from the spleens of HIV-1-infected and uninfected hNOK/B51Tg mice and of HIV-1-infected and uninfected hNOK mice at 6 weeks post-infection." (PMID 22880104, 2012). "IL-8 binds with high affinity to the G protein-coupled receptors CXCR1 and CXCR2, and the Duffy antigen receptor for cytokines, CXCR1, formerly known as the IL-8 type A receptor, which responds to high concentrations of IL-8, is most often found at sites of infection." (PMID 39062898, 2024). "Further guidance to sites of infection is provided by a family of CXCL8 chemokines originating from concentrated sites of PAMPs and DAMPs, including CXCL1, CXCL2, CXCL3, CXCL5, CXCL6, CXCL7, and CXCL8 (IL-8), which are sensed by CXCR1 and CXCR2 on neutrophils and monocytes." (PMID 30791481, 2019). "Engagement of both CXCR1 and CXCR2 induces neutrophil activation but the two receptors have distinct and non-redundant roles in inflammation and infection." (PMID 32733442, 2020). "Some of the genes with the highest robust CV had identifiable immune- and/or infection-related functions (e.g., IL1B, CXCR1), while others did not." (PMID 27658638, 2016). "On day 7 p.i., in addition to chemokines upregulated on day 3 p.i., lethal infection further induced higher expression of CCL2, CCL6, CCL11, CCL19, CCR7, CXCR1, and CXCL11 compared to nonlethal infection." (PMID 23526993, 2013).
bacterial infection (10 papers, 2014 to 2025). "CXCR1 has been shown to be downregulated in human neutrophils during bacterial infection, whereas in septic patients with organ dysfunction and septic shock, CXCR1 expression was preserved and CXCR2 expression was significantly downregulated." (PMID 28878779, 2017). "Whilst the bacterial infection increased CXCR1 expression but decreased CXCR2 expression, PKD enhanced CXCR2 expression at all stages of clinical disease." (PMID 24613851, 2014). "The concomitant increase in IL-8 and CXCR1 expression in the bacterial infection model suggests that this is a likely chemokine ligand-receptor pairing with a functional role in this disease." (PMID 24613851, 2014). "Therefore, modulation of inflammation during IAV infection by CXCR1/2 antagonists, such as DF2162, may be an interesting strategy to treat the flu and decrease the morbidity associated with secondary bacterial infections." (PMID 29326698, 2017). "Neutrophil expression of CXCR1, but interestingly not CXCR2, proved to be important for clearance of bacterial infections in vitro, and removal of CXCR1 from patient neutrophils in the airways due to proteolytic cleavage (mainly by elastase) also impaired bacterial killing." (PMID 36725964, 2023).
metabolic disease (7 papers, 2021 to 2025). A congenital disorder (due to inherited enzyme abnormality) or acquired (due to failure of a metabolically important organ) disorder resulting from an abnormal metabolic process. "While our study provides valuable insights into the role of CXCR1/2 signaling in metabolic diseases, ongoing research is essential to address remaining questions and potential safety concerns associated with therapeutic interventions targeting these receptors." (PMID 39627194, 2024). "Inhibition of the CXCL8/CXCR1 axis can protect db/db mice from metabolic diseases by regulating inflammation, as well as reducing the inflammation and apoptosis of diabetic renal tubular cells induced by high glucose." (PMID 36675322, 2023). "Given that CXCR1/2 blockade has been shown to reduce inflammation and tissue damage in diabetic complications, targeting this pathway could offer new avenues to enhance Breg differentiation and stability in metabolic disorders." (PMID 40370441, 2025). "Further in vivo studies discovered using mouse models that inducting CXCR2 was found to worsen steatohepatitis and antagonizing CXCR1 and CXCR2 protected mice from metabolic disease by a modulation of the inflammatory process." (PMID 37887430, 2023).
cardiovascular disease (4 papers, 2017 to 2022). "It has been reported that the activation of CXCR1 could be a “double-edged sword” for cardiovascular diseases." (PMID 36325326, 2022).
infectious disease (4 papers, 2010 to 2025). A disorder directly resulting from the presence and activity of a microbial, viral, or parasitic agent in humans. "In infectious diseases, CXCR2 and CXCR1 are also recognized as key regulators of NET formation." (PMID 40625358, 2025).
peripheral neuropathy (4 papers, 2017 to 2022). A disorder affecting the peripheral nervous system. "The results reported here describe for the first time the efficacy of CXCR1/2 inhibition in in vivo models of oxaliplatin-induced peripheral neuropathy." (PMID 31409858, 2019). "Overall the present results have identified IL-8/CXCR1/2 pathway as a mechanism involved in paclitaxel-induced peripheral neuropathy." (PMID 28423567, 2017). "Here, we demonstrate that oral treatment with DF2755A, a potent and selective inhibitor of chemokine receptors CXCR1/2, can prevent and reverse peripheral neuropathy associated to non-Hunner IC/BPS by directly inhibiting chemokine-induced excitation of sensory neurons." (PMID 35571079, 2022).
inflammation (3 papers, 2020 to 2024). Aberrant reaction of the microcirculation characterized by movement of fluid and leukocytes from the blood into extravascular tissues. "CXCR1/2 antagonist Ladarixin offers a new strategy for therapeutic treatment of acute and chronic neutrophilic airway inflammation, even in the context of corticosteroid-insensitivity." (PMID 33123138, 2020).
adenocarcinoma (1 paper, 2018). A common cancer characterized by the presence of malignant glandular cells. "CXCR1 has been reported as being associated with early recurrence and metastasis in low-stage adenocarcinomas." (PMID 29976164, 2018).
head and neck tumours (1 paper, 2022). "A novel pharmacological competitive inhibitor of CXCR1/2, 1-(3-chlorophenyl)-3-(6-nitrobenzo[d]thiazol-2-yl) urea, designated C29, was recently described by our team as effective in renal and head and neck tumours." (PMID 36497191, 2022).
hematologic malignancies (1 paper, 2022). "As long as CXCL16 is found in the BM at high levels and CXCL8, the CXCR1, and CXCR2 ligand is significantly elevated in MM, CLL, AML, and MDS patients, the targeting of CXCL16-CXCR6 and IL8-CXCR2/CXCR1 pathways should be studied in depth for hematologic malignancies." (PMID 35990652, 2022).
CXCR1 also shares sentences with these, for which no sentence is quoted: Lung (4 papers); fungal infection (3); rheumatoid arthritis (3); acute-on-chronic liver failure (2); cervical cancer (2); gastric tumors (2); intestinal diseases (2); steatosis (2); temporal lobe epilepsy (2); active tuberculosis (1); acute kidney injury (1); acute promyelocytic leukemia (1); Alzheimer disease (1); amyotrophic lateral sclerosis (1); Bladder Pain Syndrome (1); Bovine mastitis (1); brain injuries (1); breast diseases (1); breast infiltrating ductal carcinoma (1); breast infiltrating lobular carcinomas (1); candidiasis (1); cataract (1); cerebral aneurysms (1); chronic hepatitis (1); chronic myeloid leukemia (1); chronic periodontitis (1); crescentic glomerulonephritis (1); Crohn disease (1); cutaneous leishmaniasis (1); cystitis (1).
A further 56 diseases each share a sentence with CXCR1 in 1 paper.